CCR7 (C-C motif chemokine receptor 7)
Diseases named in the same sentence as CCR7 in open-access papers (continued):
Sharing a sentence is not in itself a finding about the gene and the disease.
tumor (continued). "The CCR7 chemokine axis plays an important role in controlling the migration of tumor cells to the lymphatic system and metastasis and therefore contributes to cancer expansion." (PMID 37963845, 2023). "Subsequently, these DCs transport tumor antigens into draining lymph nodes (DLN) in a CCR7-dependent manner; this transport is critical for the initiation of anti-tumor T cells." (PMID 37183207, 2023). "Studies have reported that CCR7 can be involved in various biological behaviors of tumor cells, such as proliferation, migration, and angiogenesis, and plays an important role in them." (PMID 37864213, 2023). "S16, B and D) and strong inflammation-related TF activation, including Irf1 and Nfkb1, akin to previously reported tumor-infiltrating CCR7+ DCs that secrete IL-12 and activate T cells to increase antitumor activity." (PMID 37075115, 2023). "The application of anti-CCR7 CAR-M successfully resulted in the suppression of immunosuppressive cell migration from tumor tissue to distal immune organs, showing effective systemic antitumor immunity in vivo." (PMID 37653035, 2023). "The MoDCs—derived in situ from tumor-infiltrating monocytes recruited by CSF-1 and CCL2—lack CCR7 expression and their anti-tumor activity would mostly entail an in situ activation of T-cell cytotoxicity in tumors." (PMID 37190135, 2023). "Cytokine-based signalling pathways, such as the CXCL13/CXCR5 axis and the CCL19,21/CCR7 axis, mediate the recruitment of B cells and TLSs in tumours." (PMID 36890557, 2023). "We observed a significant reduction in the chemokine CCL21, also referred to as secondary lymphoid tissue chemokine (SLC) and the ligand for CCR7-expressing cells, within E2-/- compared to control B6 lungs, both at homeostasis and after tumor seeding." (PMID 37426658, 2023). "Efforts to target this CCL21-CCD7 signaling axis have included CCR7-neutralizing antibodies, CCR7 agonists, specific siRNA constructs, CCR7 traps, and CCL21 mutations aimed at suppressing the lymphatic migration and invasion of tumor cells." (PMID 37752146, 2023). "MMP-9 and CCR7 positivity in tumor cells were seen in the cytoplasm and appeared as brown particles." (PMID 37600570, 2023). "Along with these observations, approximately 50% of CD8‐positive T cells in the tumor‐rejected mice showed CCR7‐positive, CD45RA‐positive stem cell memory phenotype (data not shown)." (PMID 37031457, 2023). "The expression of Ccl21a and CCR7 are undetectable in B16–F10 cells cultured in vitro and those cells in tumor tissues." (PMID 37664721, 2023). "MMP-9 activation enhances the chemotaxis and migration of LSCC tumor cells to cervical lymph nodes which is mediated by chemokine receptor 7 (CCR7)." (PMID 37600570, 2023). "A remarkable correlation has been indicated between CCR7 up regulation, regional lymph node metastasis, and tumor infiltration." (PMID 37580737, 2023). "DC subsets, in particular the cDC1 subset, migrate to tumor-draining lymph nodes and present tumor antigens to naïve T cells via a CCR7-dependent mechanism." (PMID 36949244, 2023). "Consistent with the benefit of LXR antagonism, LXR activation reduced the expres-sion of CC-chemokine-receptor-7 (CCR7) on dendritic cells (DCs) and impaired the anti-tumor response in mice." (PMID 37833991, 2023). "Tumor-derived oxysterols have been shown to downregulate CCR7 expression, thereby inhibiting DC migration to secondary lymphoid tissues and suppressing the generation of an antitumor immune response." (PMID 36949244, 2023). "Its functional significance lies in its binding to C-C chemokine receptor 7 (CCR7), a receptor that serves as a beacon guiding immune cells into the heart of the tumor tissue." (PMID 37944262, 2023). "The chemokine CCL21 was adenovirally engineered to be secreted from an anti-tumor DC vaccine to elicit signaling through CCR7 expressed on endogenous dendritic and T cells." (PMID 36167831, 2023).
tumor (continued). "When exploring tumor-infiltrating lymphocytes (TILs) after radiotherapy in patients with prostate cancer, researchers observed a higher number of CCR7+ TILs in tumor biopsies post-radiotherapy." (PMID 38264648, 2023). "As revealed by WB analyses, the expression of CXCL12, CXCR4, CCL21, and CCR7 proteins in SK-Hep1 cells was significantly increased after transfection with tumor-derived DNA in contrast to the blank control group." (PMID 35860597, 2022). "Among the altered genes related to the chemokine-mediated signalling pathway, CCR7 was most significantly upregulated in PTX-treated tumour cells." (PMID 35280672, 2022). "In tumor tissues, we obtained three T cell subtypes, including memory-like T cells (CCR7+ and CCR7_T) and exhausted CD8 (TIGIT+ and TIGIT_CD8)." (PMID 36531216, 2022). "Tumor-derived liver X-α receptor (LXRα) agonists in the TME can affect CCR7 expression in DCs since inhibition of LXRα increases protection against tumor growth." (PMID 35267487, 2022). "On the other hand, it is also well known that some tumor cells can damage the homing of DCs by suppressing their CCR7 expression to achieve immune escape." (PMID 35281921, 2022). "To further illuminate the mechanism of neutrophil recruitment, we performed analyses of CCR7 expression on LN neutrophils and observed significant upregulation of this receptor on Ifnar1-/- cells in tumor-bearing animals as compared to tumor-free mice." (PMID 35833131, 2022). "CXCR4-oe and CCR7-OE enhance the stimulation of erK1/2/MMP2/9 signaling pathway by tumor-derived DNA in HCC cells." (PMID 35860597, 2022). "By expressing CCR7+, tumor cells migrate toward the lymphatic endothelium thereby promoting lymph node metastasis." (PMID 36158182, 2022). "It will be important in future studies to confirm that the CCR7 expressed is indeed inside of the tumor cells." (PMID 35203305, 2022). "At the molecular level, CCL21/CCR7 can promote lymphatic metastasis of tumours via activating the ERK1/2 22 and JAK2/STAT3 signalling pathways." (PMID 35280672, 2022). "In many reported cases of these types of malignant cancers, increased size of tumor and invasions were due to CCR7." (PMID 35874608, 2022). "Cancer cells overexpressing CCR7 were injected subcutaneously into mice, and the animals were monitored for tumor growth along with lymph node metastasis." (PMID 36243683, 2022). "It has been demonstrated that CCL21/CCR7 signalling axis plays a crucial role in the lymphatic metastasis of many tumours." (PMID 35280672, 2022). "Once the capacity of 4PD to bind and transfect myeloid cells in vivo with multiple shRNAs was determined, we evaluated the effect of chronic CCR1, CCR2, CCR5, and CCR7 silencing on tumor progression." (PMID 35064009, 2022). "Cluster #4 presented with the most abundant expression of maturation markers including LAMP3, CD80, CD40, the migration marker CCR7, and overexpressed the tumor Secretory cDC2 signature, thus #4 was labeled mmDC." (PMID 35418195, 2022). "Merad and colleagues recently identified an immunoregulatory DC that expresses PD-L2 and CCR7, in both tumor-bearing mice and humans with NSCLC." (PMID 35493454, 2022). "Tumor-derived oxysterols such as 22(R)-hydroxycholesterol and 27-hydroxycholesterol can exert opposite effects on the expression of CCR7 in dendritic cells." (PMID 35455931, 2022). "Several studies have revealed that CCL19 and CCL21 can vigorously drive the chemotaxis migration of CCR7-expressing tumor cells." (PMID 35874608, 2022). "Our result (observed upregulation of the CCL19/CCR7 axis on mRNA expression level), in a macroscopically unchanged area surrounding the tumor, confirms the presence of immunological/molecular variations in this tissue." (PMID 35160116, 2022). "It has been reported that CCL19, as a chemokine, can promote the release of cytokines by CD8+ T cells by binding to its receptor CCR7, thereby inhibiting the proliferation, migration, and invasion of tumor cells." (PMID 36189258, 2022).
tumor (continued). "When injected into nude Balb/c mice, small hairpin RNA inhibitor of CCR7 led to decreased tumor size compared to control Ba/F3, suggesting that CCR7 is required for the STAP-2/BCR-ABL-induced CML growth." (PMID 35203305, 2022). "In turn, downregulating the expression of CCR7 or blocking the CCL21/CCR7 axis ultimately led to the decrease in migration of tumour cells after PTX chemotherapy." (PMID 35280672, 2022). "The expression of PD-1, ICOS, and CCR7 on T cells in tumor tissues was significantly higher than that of T cells in paratumor tissues." (PMID 35725444, 2022). "Enhanced expression levels of CXCR4, CXCR5 and CCR7 were found in tumor tissues compared to normal tissue." (PMID 35203305, 2022). "The primary genes reduced by CCR7 activation were in the interferon-γ pathway, suggesting downregulation of host anti-tumor immunity." (PMID 35203305, 2022). "The tumor-infiltrating immune cell models in TIMER2.0 database depicted that the expression of CCR7 promotes M2 macrophages infiltration level and correlates with M2 biomarkers in OSCC." (PMID 35904690, 2022). "Except for NOS1, DNMT1 and CCL5, the hub genes CCL19 and CCR7 in DE-GRGs are compose of the CCL19/CCL21-CCR7 axis that exerts both immune response and tumor proliferation." (PMID 35517412, 2022). "For example, CCR7-dependent maturation of DCs, as well as their migration to draining lymph nodes where they exert their anti-tumor immune responses, are inhibited by tumor-derived oxysterols." (PMID 35945203, 2022). "CCR7, however, plays a unique role in tumorigenesis by targeting tumor cell metastasis to the T-cell zones of lymph nodes." (PMID 35203305, 2022). "The conducted meta-analysis showed that higher expression of CCR7 can independently be used as an indicator of poorer OS in patients having a tumor." (PMID 35874608, 2022). "Lymph node status correlated with CCR7 expression by immunohistochemical analysis of 99 colorectal patients at various clinical stages of tumor progression, although, overall, 5 year survival was significantly lower for CCR7-positive tumors." (PMID 35203305, 2022). "The link between HIF-1α and CCR7 in tumor lymph node metastasis was previously discussed, whereas the relevance of STX1A, a typically nervous system-specific protein, is unclear." (PMID 35203305, 2022). "cDC1 cells, which are IRF8-dependent, and express CD141 and CCR7, move from the tumor site to lymph nodes, activating CD8+ T anti-tumor cells." (PMID 35269652, 2022). "We used the 4PD nanoparticle for the in vivo targeted silencing of CCR1, CCR2, CCR5, and/or CCR7 in the myeloid cells of tumor bearing mice to evaluate the effect of treatments on tumor growth, myeloid cell trafficking and polarization." (PMID 35064009, 2022). "The mechanisms of the tumor-promoting effect of CCR7 include the induction of tumor angiogenesis by activating NF-κB and increasing VEGF expression, epithelial–mesenchymal transition of cancer cells and migration of cancer cells to metastasis sites." (PMID 35123499, 2022). "CCR7-siRNA can inhibit the migration of tumour cells by reducing CCL21/CCR7 binding by inhibiting CCR7 expression at mRNA level." (PMID 35280672, 2022). "Immune and stromal cell populations included 2 populations: Macrophages 1 (c1: C1qa, C1qb, C3aR1, Cd68, Csf1r, Tlr2, and Cd86) and 2 (c6 + c9: Ccr7, Csf2rb, Il1b, and Cd74) expanded in PNs as a percentage of total tumor cells." (PMID 36134665, 2022). "It is known that CCR7 can be expressed by various subsets of immune cells, such as DCs, T cells, and B cells, as well as some tumor cells, acting as a key adjustor in guiding them to destinations." (PMID 35281921, 2022). "VEGFC accumulated in the tumor context induces tumor lymphatic vessels to release chemokines such as CCL19 and CCL21 that can attract tumor cells through their binding to CCR7." (PMID 36612017, 2022). "In the future, it will be important to correlate stage of progression with the types of cells within a tumor that express CCR7." (PMID 35203305, 2022).
tumor (continued). "The results of this meta-analysis suggested that in some types of tumors, the overexpression of CCR7 is correlated to the worst prognosis of tumor patients." (PMID 35874608, 2022). "In melanoma, CD103+ DCs transport tumor antigens to Draining lymph nodes (dLN) in a CCR7-dependent manner, resulting in increased numbers of tumor-specific CD8+ T cells." (PMID 36313679, 2022). "In PTC, CCR7 has been found to show strong correlations with tumor aggressiveness indicators and tumor size." (PMID 35692574, 2022). "This group previously found that lipid droplet high (LDhi) immunosuppressive cells expressed CC-chemokine receptor 7 (CCR7), accumulated in tumor tissues, and suppressed anticancer immunity." (PMID 35361234, 2022). "The expression levels of CCR7 and let-7a were measured in the cell lines, tumor, and peritumoral tissues of ESCC patients." (PMID 36243683, 2022). "Apoptosis of SK-Hep1cells was significantly reduced after treatment with tumor-derived DNA combined with CXCR4 or CCR7 overexpression but increased after treatment with sinocine hydrochloride." (PMID 35860597, 2022). "It has been reported that the CCL19/CCL21/CCR7 axis functions in immune cells and helps cells migrate to SLOs or other tumor sites and activate the host cell response." (PMID 34689225, 2022). "Upregulation of the CCL21/CCR7 axis results in the migration of tumour cells from primary to lymphatic vessels, promoting lymphatic metastasis of various tumours." (PMID 35280672, 2022). "TGF-β inhibits the expression of CCR7 on DCs, thereby leading to reduced ability of DCs to migrate to the tumor-draining lymph nodes." (PMID 35372586, 2022). "The CCL21-CCR7 axis has also been shown to be an important lymphatic regulator of metastasis; tumor expression of CCR7 increases lymph node metastasis in mouse models, while neutralization of the CCR7 ligand CCL21 in lymphatics decreases lymph node metastasis." (PMID 35216243, 2022). "These experiments indicate that hsa-let-7e-5p acts as a tumor suppressor by inhibiting CCR7 actions." (PMID 35203305, 2022). "On the other hand, the CCL19/CCR7 axis is involved in the modulation of the immune response in a growing tumor." (PMID 35160116, 2022). "Blocking the CCL21/CCR7 axis signalling pathway significantly inhibits the migration of tumour cells treated with PTX." (PMID 35280672, 2022). "Enrichment for CCR7 expression produces a dendritic cell therapy product with enhanced migratory ability able to generate a powerful anti-tumor response." (PMID 36230990, 2022). "CXCR4 siRNA and CCR7 siRNA attenuated tumor-derived DNA activation of ERK1/2/MMP2/9 signaling pathways in HCC cells." (PMID 35860597, 2022). "Since CCR7 is also expressed at hair follicles and intestinal villi, on-target off-tumor toxicities were observed when high-dose CAR-M (MerTK) was administered." (PMID 35361234, 2022). "From pre-clinical models, we know that the use of anti-CCR7 mAbs selectively inhibited and/or depleted tumor cells while sparing healthy counterparts." (PMID 34778050, 2021). "PLA was performed using unconjugated anti-CXCR4 and anti-CCR7 antibodies, together with an Alexa Fluor® 488 anti-EpCAM antibody to distinguish epithelial tumour areas from tumour stroma for subsequent quantitation." (PMID 34685420, 2021). "In these studies, such anti-CCR7 therapies reduced tumor cell migration and infiltration into CCR7-specific environments and additionally impaired survival/proliferation." (PMID 34778050, 2021). "Whereas different organs can attract CXCR4-expressing tumor cells, CCR7 expression is mainly a prerequisite for dissemination to secondary lymphoid organs." (PMID 34503058, 2021). "First, it causes the establishment of a self-enhancing loop that recruits more CCR7-expressing tumor and accessory cells favoring the creation of a protective and tolerogenic microenvironment." (PMID 34778050, 2021).
tumor (continued). "The silencing of CCR7 gene expression through siRNA or miRNA led to decreased metastasis and tumor growth in models of prostate, breast and colorectal cancer." (PMID 34575965, 2021). "Nonetheless, recent evidence suggests that CCR7 is more than a facilitator of lymphatic spread of tumor cells." (PMID 34778050, 2021). "In comparison with DC2, DC1 uptake antigen and migrate out of the tumor with increased efficiency in accordance with their higher expression of CCR7 and Clec9a." (PMID 34283809, 2021). "Nonetheless, targeting CCR7 in cancer has the potential downsite of activating and/or potentiating alternative pathways that would eventually allow homing of tumor cells to protective niches." (PMID 34778050, 2021). "In vivo studies revealed that metastatic tumour formation is decreased when CCL21 expression is knocked down in secondary lymphoid organs, since this diminishes both the chemotactic and antiapoptotic effects of CCR7-expressing tumour cells." (PMID 34298676, 2021). "Related studies have demonstrated that NR1H3 can impair the anti-tumor response by inhibiting the CCR7 expression on dendritic cells, suggesting a novel mechanism for immune escape." (PMID 34136377, 2021). "We confirmed the control of the main chemokine/receptor axes, CXCL12/CXCR463 and CCL21/CCR7,11, 64 involved in tumour escape and verified their dependency on hypoxia." (PMID 33624446, 2021). "Treatment with Sulfotransferase 2B1b (SULT2B1b), an LXR ligand-inactive enzyme, relieves the CCR7 inhibition in DCs, and restores DC function and the anti-tumor response." (PMID 34820325, 2021). "VEGFC can upregulate the expression of CCL21 in lymphatic vessels, driving tumor cells to express CCR7, and enhance the invasive phenotype of tumor cells." (PMID 34552874, 2021). "They studied CCR7 expression in skin biopsies from six patients with early disease and six patients at the tumor stage." (PMID 34778050, 2021). "Vaccination with rlipoE7m-MoGM therapy increased the number of CCR7+CD103+ cDC1s, whereas the number of suppressive tumor-associated macrophages was reduced in the tumor lesions." (PMID 34599024, 2021). "These cDC1s and cDC2s had increased expression of CD86, MHC-II and CCR7, suggesting that these cells were highly activated and developed migratory potential towards the tumor-draining LN." (PMID 33408092, 2021). "The results indicated that CCL19 expressed by tumor cells had a chemotactic effect on CCR7-positive T cells." (PMID 34527749, 2021). "Previous microarray analyses have reported overexpression of the lymph node homing receptor CCR7 in the dermis of tumor-stage MF." (PMID 34204115, 2021). "Using IHC, they found no expression of CCR7 in any tested sample, however, two skin samples of advanced disease showed strong and uniform expression of CCR7 on tumor cells by flow cytometry." (PMID 34778050, 2021). "We and others believe that this effect is likely due to a lower target density in non-tumor cells or to a lower affinity of these antibodies for CCR7 expressed in these cell types." (PMID 33841445, 2021). "Overall, the combined neutralizing and killing activities of anti-CCR7 mAbs led to retarded tumor implantation, reduced tumor burden, and significantly extended host survival in in vivo models." (PMID 34778050, 2021). "VEGF-C can mediate the upregulation of CCL21 secretion in lymphatic endothelium, which drives CCR7-dependent tumor chemo invasion towards lymphatics." (PMID 33390169, 2021). "CCR7-positive staining was observed in the tumours of 2 of 10, 1 of 12, and 0 of 6 Cfms-rtTA, TetO-TbrII and Cfms-TbrII mice, respectively." (PMID 33761981, 2021). "In both cases, CCR7-positive cell lines showed earlier lymphatic tumor spreading compared to CCR7-negative cells." (PMID 34830848, 2021). "In in vivo pre-clinical studies, we confirmed CCR7 to play critical roles in enabling tumor cells to access tumor microenvironments in CNS and lymphoid organs, especially in LN." (PMID 34778050, 2021).